LGALS3 (galectin 3)
Diseases named in the same sentence as LGALS3 in open-access papers (continued):
Sharing a sentence is not in itself a finding about the gene and the disease.
chronic heart failure (continued). "There are reports where galectin-3 has been utilized as a marker to follow the inflammatory activity of a disease or used as a factor for prognosis in cancers or chronic heart failure." (PMID 25033447, 2014). "A 26-month study involving patients with chronic heart failure and CAD revealed that galectin-3 values > 21 ng/mL were associated with elevated mortality risk, establishing galectin-3’s independence as a predictor for mortality from all causes and rehospitalization." (PMID 38255650, 2023). "In addition, galectin-3 positively correlated with PWV in patients with chronic heart failure and hemodialysis after adjustment for confounders." (PMID 34437403, 2021). "Serum galectin-3 levels predict response and long-term outcomes after cardiac resynchronization therapy in chronic heart failure patients and may help select patients requiring closer monitoring." (PMID 30390680, 2018). "Galectin-3 plasma levels (gal-3) were shown to correlate with the scar burden in chronic heart failure (CHF) setting." (PMID 31885743, 2019). "Galectin-3 promotes adverse cardiac remodeling leading to chronic heart failure (CHF)." (PMID 36158385, 2022). "Other studies have investigated the role of Galectin-3 levels both in AMI and chronic heart failure, using experimental models of AMI and human studies." (PMID 31511537, 2019). "We therefore sought to explore a correlation between changes in galectin-3 plasma levels and response to transendocardial CD34+ cell transplantation in patients with chronic heart failure." (PMID 31885743, 2019). "We evaluate the relevance of a multiparametric biomarker approach based on increased serum levels of NT-proBNP, galectin-3, and ST2 in stratifying the prognosis of chronic heart failure (CHF) outpatients." (PMID 29367540, 2017). "Interestingly, considering the role of galectin-3 in inflammatory and fibrotic processes, the U.S. Food and Drug Administration (FDA) has approved galectin-3 measurements as a prognostic biomarker in chronic heart failure." (PMID 41226478, 2025). "Additionally, the optimal threshold points of galectin-3, RDW, Hepc, HS and ferritin for predicting the prognosis of patients with acute exacerbation of chronic heart failure were 31.287 ng/ml, 48.769 fL, 102.969 ng/mL, 199.389 μg/L, 23.022 ng/mL, respectively." (PMID 36348283, 2022).
glioma (54 papers, 2010 to 2025). A benign or malignant brain and spinal cord tumor that arises from glial cells (astrocytes, oligodendrocytes, ependymal cells). "High LGALS3 expression was significantly associated with worse overall survival in lower-grade glioma, PDAC, uveal melanoma, and kidney renal papillary cell carcinoma." (PMID 41153387, 2025). "Accumulating evidence has proven the immune system has an essential role in malignancy pathogenesis, and LGALS3 is closely correlated with CD163+ tumor-associated macrophages (TAM) in glioma." (PMID 38643145, 2024). "After further staining for galectin-3, implicated in glioma progression, as well as in membrane damage and other cellular processes, we observed a significant increase of galectin-3 staining after AF16 + TMZ compared to controls (p = 0.029)." (PMID 35301393, 2022). "Galectin 3 is associated with glioma progression and neo-angiogenesis but also with membrane damage, with galectin 3 being upregulated after temozolomide and radiotherapy treatment." (PMID 35301393, 2022). "Herein, we show that Tmem119 is highly expressed by MG (both in control and glioma conditions), and Lgals3 (encoding Gal-3) by infiltrating Mo/MΦ at RNA and protein levels." (PMID 33608526, 2021). "Multivariate Cox analysis confirmed that LGALS3 was an independent risk factor for survival in diffusely infiltrating glioma with an adjusted HR of 1.537 (95% CI: 1.204–1.987, p = 0.031)." (PMID 32528967, 2020). "The association between LGALS3 and glioma clinically relevant diagnostic/molecular markers (IDH, 1p19q, ATRX, MGMT, and TERT) was examined using the Chi-Squared (χ2) test." (PMID 32528967, 2020). "LGALS3 is associated with poor prognosis in diffusely infiltrating glioma and served as an important prognostic biomarker in LGG and GBM." (PMID 32528967, 2020). "Galectin-3, a glioma-related marker encoded by LGALS3, is a β-galactosidase-binding lectin that is important in cell proliferation, adhesion, and apoptosis." (PMID 31075138, 2019). "However, the mechanism by which LGALS3 affects the glioma immune microenvironment and the exact pathways associated with LGALS3 in glioma need to be further explored in future studies." (PMID 32528967, 2020). "This process promotes LGALS3 secretion, inducing mesenchymal transformation of glioma stem cells and M2 macrophage polarization." (PMID 40090864, 2025). "For this reason, galectin 3 was suggested as a potential biomarker for the early diagnosis of glioma." (PMID 39684236, 2024). "Our cophenetic correlation coefficient calculations (CCC) are in support of EMMPRIN/CD147, CD99, Cathepsin D, Intβ1, ADAM9/-17, and Galectin-3 being suitable biomarkers for glioma cells and potentially, SLGCs." (PMID 38306361, 2024). "In GL261 gliomas, the infiltration of galectin-3+ macrophages and CD8 + T lymphocytes into the tumor mass was similar for both WT and SorLA-KO mice." (PMID 38499808, 2024). "This makes LGALS3 a promising therapeutic target to regulate anti-tumor immunity in several kinds of cancer, including glioma, breast, lung, as well as prostate tumors." (PMID 38643145, 2024). "Galectin-1 and Galectin-8 have been shown to participate in glioma invasion, and Galectin-1 and Galectin-3 can reportedly promote immunosuppression in glioma microenvironments." (PMID 35814469, 2022). "For instance, LGALS3, L1CAM, and SCAMP3 were associated with the shorten OS of glioma patients by promoting the proliferation or other malignant tumor characteristics of glioma." (PMID 33750478, 2021). "We observed significantly elevated level of Galectin-3 BP in individual plasma specimens from glioma (Gr I, II, III) patients as compared with healthy individuals." (PMID 34900729, 2021). "In various glioma cell lines, variable results were seen in the adhesion of cells to galectin-3 substrate, with some cell lines showing minimal adhesion, while others displayed a significant amount." (PMID 35008740, 2021).
glioma (continued). "Kaplan-Meier analysis and the Cox regression analysis were applied to evaluate the prognostic value of LGALS3 in glioma." (PMID 32528967, 2020). "To better understand the biological function of LGALS3 in glioma, we further researched genes correlated with LGALS3 expression in TCGA, Rembrandt, and Gravendeel databases using Pearson's correlation analysis (|r|≥ 0.3)." (PMID 32528967, 2020). "In this study, we detected the expression of LGALS3 in a large number of glioma samples and found that LGALS3 was highly expressed in pilocytic astrocytoma and GBM." (PMID 32528967, 2020). "Some studies have also confirmed that LGALS3 played a key role in glioma development through increasing cell motility and invasion." (PMID 32528967, 2020). "The purpose of our research is to detect LGALS3 expression and its prognostic value in glioma and reveal the relationship between its expression and the clinico/molecular-pathological features of patients and immune cell infiltration." (PMID 32528967, 2020). "Most importantly, we found that LGALS3 was involved in the regulation of the glioma immune microenvironment, particularly CD163+ TAMs." (PMID 32528967, 2020). "In the present study, we investigated the relationship between LGALS3 and TAMs in a large sample (304 glioma cases including 133 cases of GBM)." (PMID 32528967, 2020). "Compared with that in other types of glioma and normal tissues, the expression of LGALS3 was also significantly higher in GBM and was mainly expressed in classical and mesenchymal GBM subtypes." (PMID 32528967, 2020). "LGALS3 was mainly expressed in cytoplasm, and weak expression in endothelial cells was used as an internal control in glioma." (PMID 32528967, 2020). "Studies of the relationship between Runx2 and Galectin-3 demonstrated that Runx2 mediated the expression of Galectin-3 in skeletal tissue, human glioma cells, and human pituitary tumor." (PMID 28264434, 2017). "Galectins 1, -2, -4, -7, -8 and -9 are expressed in human brain and Galectin-1, Galectin-3 (Gal-3) and Galectin-8 (Gal-8) are the most abundantly expressed in human glioma cell lines." (PMID 27459991, 2016). "Galectin-3, one of the most important factors in cell invasion process, was reported to be modulated by MMPs, which plays a crucial role in glioma cell invasion." (PMID 27026929, 2016). "Therefore, they propose incorporating galectin-3 inhibitors into treatment regimens for these gliomas as a promising strategy to improve treatment efficacy while controlling toxicity, thereby enhancing patients’ overall quality of life." (PMID 40948781, 2025). "Although galectin-3 is a proven immunomodulator, it is also considered as a glioma-related marker." (PMID 40895574, 2025). "Indeed, an increase in macrophages expressing high levels of Spp1, ApoE, Apoc1, Lgals3, and Gpnmb has been documented in glioma models, with high‐grade gliomas exhibiting a greater abundance of these macrophages compared to low‐grade gliomas." (PMID 40395129, 2025). "To date, the role of galectin-3 in the glioma TME has been scarcely studied." (PMID 35008740, 2021). "On the other hand, galectin-3 overexpression in the glioma T98G and U251 cell lines resulted in increased growth rates, suggesting that this lectin could promote glioma cell proliferation." (PMID 35008740, 2021). "Recent evidence indicated that galectin-3 also controls glioma cell survival." (PMID 35008740, 2021). "Galectin-3 BP threshold value to predict the mortality rate in glioma patients is depicted in." (PMID 34900729, 2021). "The accuracy of Glioma Galectin-3 BP EVs protein concentration ng/ml was 45.0%, respectively." (PMID 34900729, 2021). "Interestingly, a number of studies highlighted a potential role of galectin-3 as an oncogenic factor that contributes to glioma cell growth." (PMID 35008740, 2021). "Clinical-pathological characteristics of the glioma patients and LGALS3 expression." (PMID 32528967, 2020).
glioma (continued). "LGALS3 was an independent poor prognostic marker in diffusely infiltrating gliomas and was positively correlated with immune cell infiltration, particularly CD163+ tumor-associated macrophages in the TCGA dataset, Rembrandt dataset, and our SYSUCC cohort (R = 0.419, 0.627, and 0.724)." (PMID 32528967, 2020). "All these results indicated that LGALS3 may be involved in the immunosuppression in the glioma microenvironment by regulating the immune response and influencing the proportion of infiltrating immune cells (particularly TAMs)." (PMID 32528967, 2020). "Regarding prognosis, Kaplan-Meier analysis also revealed that LGALS3 was a significant poor prognostic marker in diffusely infiltrating glioma, and it was a clear indicator of poor prognosis in both LGG and GBM regardless of whether chemotherapy was used." (PMID 32528967, 2020). "LGALS3 was mainly expressed in IDH wild-type glioma and was closely related to CD163+ TAMs." (PMID 32528967, 2020). "A series of studies confirmed the oncogenic properties of LGALS3 expression in glioma." (PMID 30848102, 2019). "Galectin-3 is activated in microglia and macrophages according to the progression of glioma, however, it is not expressed in oligodendrocytic cells representing the early stage of glioma tumorigenesis." (PMID 31075138, 2019). "Studies showed that high levels of Galectin-3 expressed in high grade glioma." (PMID 27026929, 2016). "In addition, galectin-3, a β-galactoside-binding protein that in its soluble form can induce T-cell apoptosis, was found to be secreted by the glioma CSCs." (PMID 24728412, 2014). "RUNX1 and RUNX2 upregulate LGALS3 (galectin-3), a protein which suppresses anoikis and drug-induced apoptosis and whose expression is correlated with metastasis in osteosarcoma and progression in glioma." (PMID 20465837, 2010). "It has been reported that Galectin-3 may contribute to immunosuppression in glioma." (PMID 35814469, 2022). "However, the clinical significance and biological functions of LGALS3 in glioma remain virtually unknown." (PMID 32528967, 2020). "This may explain why LGALS3 positive glioma patients have a significantly shorter OS than LGALS3 negative patients, suggesting that LGALS3 may play a role in malignant progression in glioma through changing the immune microenvironment in glioma." (PMID 32528967, 2020). "In addition, the observation of a higher expression level of Lgals3 in the three invasive neoplastic cell lines compared with the non invasive M5-T2 suggests a relation with the tumor grading, as previously demonstrated in human gliomas." (PMID 27129173, 2016). "In lower-grade glioma (LGG), high LGALS3 expression corresponded to a hazard ratio (HR) of 2.0 with a p-value of 3.48 × 10−6." (PMID 41153387, 2025). "In glioma cells, the silencing of LGALS1 and LGALS3 resulted in decreased resistance to radiotherapy, while DNA damage induced by radiation was increased." (PMID 39337581, 2024). "LGALS3 was closely related to IDH status, CD163+ TAMs and was mainly expressed in IDH wild-type glioma." (PMID 32528967, 2020). "We found that CD163+ TAMs were abundant in glioma, particularly in GBM and that LGALS3 was strongly correlated with the number of TAMs." (PMID 32528967, 2020). "Further stratification analysis revealed that LGALS3 was also a poor prognostic marker in LGG, GBM, anaplastic astrocytoma, and IDH wild-type glioma." (PMID 32528967, 2020). "Among the galectins analysed, LGALS1, LGALS3, and LGALS9 emerged as significantly upregulated in glioblastoma, consistent with prior studies identifying these molecules as key contributors to glioma progression and suggesting multifaceted roles in tumour progression and resistance mechanisms." (PMID 41516291, 2025). "Additionally, glioma cluster 2 cells expressed selectins (LGALS1 and LGALS3), integrins (ITGB1), and glycosylation targets (VIM, TIMP1, HIF1A, and CD44)." (PMID 39333557, 2024).
glioma (continued). "In this regard, another study suggested that galectin-3 was also induced under hypoxic conditions through HIF-1α- and NF-kB-dependent mechanisms and could protect glioma cells from cell death induced by hypoxic and nutrient deprivation conditions." (PMID 35008740, 2021). "Although there are a number of studies reported that suggest the involvement of Galectin-3 in gliomas, the LGALS3BP is not widely studied yet." (PMID 34900729, 2021). "Kaplan-Meier plots revealed that LGALS3 expression was a significantly unfavorable prognostic marker in diffusely infiltrating gliomas (WHO II-IV) but not in pilocytic glioma (WHO I)." (PMID 32528967, 2020). "Of interest, the rat glioma cell line C6 did not adhere at all to galectin-3." (PMID 35008740, 2021). "Although GBM and pilocytic astrocytoma expressed LGALS3 with similar patterns, pilocytic astrocytoma is a distinct histologic and biologic subset of glioma that is characteristically slow-growing and non-infiltrative and targets totally different pathways compared with GBM." (PMID 32528967, 2020). "Interestingly, galectin-3 is expressed by glioma cells, but not by astrocytes or oligodendrocytes." (PMID 24728412, 2014).
chronic kidney disease (52 papers, 2014 to 2025). Impairment of the renal function secondary to chronic kidney damage persisting for three or more months. "Galectin-3 has been proposed to contribute to the pathogenetic processes of both acute kidney injury and chronic kidney disease, while its serum levels present an inverse association with kidney function." (PMID 38519721, 2024). "High concentrations of galectin-3 in plasma have been associated with a risk of chronic kidney disease and are reduced using hemodialysis treatments." (PMID 36292107, 2022). "In individuals experiencing renal failure, a rise in galectin-3 concentration is linked to kidney fibrosis, elevated chances of fast renal function decrease, the occurrence of chronic kidney disease, advanced renal impairment, and death." (PMID 36648873, 2022). "In patients with altered renal function, increased plasma levels of galectin-3 have been associated with higher risk of renal function decline, incident chronic kidney disease, and renal failure." (PMID 35008648, 2021). "Specifically, evidence coming from the combined analysis of the Seattle Kidney Study and the Clinical Phenotyping and Resource Biobank Study pointed toward an increased risk of mortality with higher serum galectin-3 levels among patients with pre-dialysis chronic kidney disease." (PMID 38519721, 2024). "Current data suggest that galectin-3 levels may be also linked to adverse clinical outcomes in patients with earlier stages of chronic kidney disease." (PMID 38519721, 2024). "Elevated levels of plasma galectin-3 are also associated with increased risks of rapid renal function decline, incident chronic kidney disease, and progressive renal impairment, and also with cardiovascular end points, infection, and all-cause mortality in patients with renal function impairment." (PMID 27089335, 2016). "Galectin 3 plays a significant role in the development of chronic renal failure, particularly end-stage renal disease (ESRD)." (PMID 35807161, 2022). "Galectin-3 is a β-galactoside-binding lectin, involved in various biological processes including pathogenesis of chronic renal disease." (PMID 28487598, 2017). "Using an experimental mouse model of chronic kidney disease and human epithelial cell lines, we investigate the role of Galectin-3 in dividing epithelial cells." (PMID 28469279, 2017). "Moreover, LGALS3 has been implicated in the development of both AKI and chronic kidney disease (CKD)." (PMID 39042141, 2024). "Likewise, the development of chronic kidney disease produces a decrease in the clearance of galectin-3, leading to a further increase in the circulatory system." (PMID 36292107, 2022). "We identified chronic kidney disease as an independent determinant of galectin-3 concentrations in patients with a central catheter, and serum creatinine, cardiovascular disease, and number of days that the catheter was indwelling were identified as determinants in urinary catheter patients." (PMID 36292107, 2022). "Galectin-3 facilitates profibrotic signaling and immune activation, contributing to conditions like chronic kidney disease (CKD) and acute kidney injury (AKI)." (PMID 39769262, 2024). "Similarly, in children with end-stage renal disease undergoing regular hemodialysis, galectin-3 was identified as an early marker of diastolic dysfunction, underscoring its potential role in the early detection and monitoring of cardiac involvement in pediatric CKD." (PMID 39063659, 2024). "An important role of galectin-3 was found in the etiology of chronic kidney disease in addition to acute renal damage (CKD)." (PMID 36648873, 2022). "In individuals with chronic kidney disease (CKD), galectin-3 levels were correlated with echocardiography parameters indicative of diastolic dysfunction, suggesting its utility as a biomarker for cardiac fibrosis and dysfunction in this population." (PMID 39063659, 2024).
chronic kidney disease (continued). "Galectin-3 is also elevated in non-cardiac conditions, such as chronic kidney disease, cancer and systemic inflammation, potentially reducing its specificity for MI." (PMID 39941683, 2025). "In patients with chronic kidney disease (CKD) and on dialysis, galectin-3 could predict cardiovascular morbidity, infection-related death, and all-cause mortality." (PMID 37240626, 2023).